ERAP2 (endoplasmic reticulum aminopeptidase 2)
Diseases named in the same sentence as ERAP2 in open-access papers (continued):
Sharing a sentence is not in itself a finding about the gene and the disease.
tumor (continued). "Statistical analysis of the 132 paired samples available from these 157 patients demonstrated that ERAP2 expression was significantly higher in tumor cells versus normal epithelial cells (157.1 ± 79.04 vs. 5.0 ± 20.73, respectively; P < 0.001)." (PMID 28977897, 2017). "Taken together, these studies suggest that normal function of ERAP1 and ERAP2 is required for NK cell- and T cell-mediated anti-tumor immunity." (PMID 25566501, 2014). "The availability of specific ERAP1 and ERAP2 antibodies has allowed researchers to investigate the expression and tissue distribution of these enzymes in a large number of tumor cells of various origins." (PMID 25566501, 2014). "ERAP2 plays a role in activating PSCs, exacerbating tumor progression through autophagy." (PMID 36834865, 2023). "The immune response escape of tumor cells by the imbalance of ERAP2/ERAP1 was further supported by prior studies, in which a decreased HLA class 1 surface expression was observed together with this imbalance, thereby reducing the tumor-associated peptide antigen presentation." (PMID 37372322, 2023). "In contrast to the results in CRA00160, the mean UMI count of ERAP2 in GSE212966 was lower in tumor samples, which could be accounted for by the low proportion of detected malignant cells." (PMID 37251940, 2023). "Inhibition of ERAP2 activity may be an effective method to improve tumor antigenicity, but the specific mechanisms need to be further elucidated." (PMID 36214762, 2022). "Contingency table for expression of ERAP2 and tumor grade in KIRC." (PMID 32082366, 2019). "Therefore, the absence or presence of ERAP1 and ERAP2 could change the peptide repertoire of trophoblast or tumor cells, increasing immune tolerance and allowing for increased proliferation and invasion." (PMID 36834865, 2023). "At the single-cell level, tumor cells expressed low levels of CHST11 compared with ALDH3B1, EGFR, ERAP2, MSLN, and NCEH1." (PMID 37251940, 2023). "The intratumoral heterogeneity was also explored using the Tumor Purity value, with which CXCL11, ERAP2, FYN, GH1, MAP3K14, and SEMA6C were found negatively correlated, while the rest were positively correlated." (PMID 36428747, 2022). "Thus, the tumor cells of HLA class I positive HL cases show normal ERAP1 and ERAP2 expression patterns." (PMID 33499248, 2021). "The expression and tissue distribution of ERAP1 and ERAP2 have been evaluated in a large number of tumor cells of lymphoid and non-lymphoid origin compared to their normal counterparts." (PMID 22942706, 2012). "In addition, ERAP2 knockdown decreased the PSC’s ability to promote migration and the invasion of pancreatic ductal adenocarcinoma (PDAC) by inhibiting ER-derived autophagy, and, in vivo xenografted tumor growth and fibrosis." (PMID 40226591, 2025). "While it was documented that the expression of ERAP1 and ERAP2 is frequently altered in tumors compared to that in normal cells, only a few investigations have been conducted on how the altered expression of ERAP genes affects tumor growth and anti-tumor immune response." (PMID 36834865, 2023). "ERAP2 expression in positive groups was significantly higher than in negative groups for all three immune markers, implying ERAP2 may exert significant functions in anti-tumor immunity." (PMID 34992605, 2021). "Furthermore, protein level of ERAP2 is elevated in tumor tissues compared to their noncancerous counterparts." (PMID 28977897, 2017). "Notably, upregulation of ERAP1 and ERAP2 in ERAP-low tumor cells was found to enhance HLA class I surface expression, suggesting that abnormal HLA class I levels in tumor cells may result from defective expression of these enzymes." (PMID 25566501, 2014). "Therefore, whereas of interest in light of the specialized role and regulation of ERAP2, the selective non-rescuability of this aminopeptidase in some NB cell lines is not expected to affect the processing of most antigens, including tumor antigens." (PMID 23071666, 2012).
infection (14 papers, 2017 to 2025). The state of being infected such as from the introduction of a foreign agent such as serum, vaccine, antigenic substance or organism. "In this review, we summarise the evolutionary history of human ERAP2 haplotypes and discuss how natural selection helped shape allelic diversity that influences susceptibility to chronic inflammatory disease and infection resistance." (PMID 37925533, 2023). "According to current data, haplotypes of ERAP2 have opposing genetic association with chronic inflammation and infection." (PMID 37925533, 2023). "Selection for functional ERAP2 is thought to have arisen as a protective mechanism towards infection." (PMID 39123229, 2024). "Selection for functional ERAP2 is thought to have arisen as a protective mechanism towards infection, supported by several recent studies." (PMID 39123229, 2024). "Studies of HIV-1 exposed seronegative individuals have found that ERAP2 genotype AA is overrepresented, suggesting possible effects operating at acquisition of infection and distinct from antigen processing for antiviral T cell responses." (PMID 38980912, 2024). "We also show that the interaction of ERAP2 and other known genetic factors explains greater variation in infection outcome than these factors alone." (PMID 38980912, 2024). "This emphasizes the importance of studying ERAP2 under physiological inflammatory conditions (during infection and inflammation) and in primary tissues to answer outstanding questions regarding its biological functions." (PMID 37925533, 2023). "rs72773986 is an infection eQTL and a GTEx eQTL for ERAP2, and is predicted to alter binding of EPAS1, a key transcription factor for response to hypoxia." (PMID 34570765, 2021). "First, there was significant correlation between overall flu transcript abundance, a proxy for degree of infection, and ERAP2/Iso3 and ERAP2/Iso4 transcript abundances and usages in heterozygotes and Haplotype B homozygotes." (PMID 30446528, 2018). "We extended our earlier study to determine whether variation in ERAP1 and ERAP2 influences infection outcome." (PMID 38980912, 2024). "To verify whether ERAP2/Iso3 expression varies in response to growing viral concentrations we adopted two in vitro model of infection." (PMID 32847031, 2020). "These cells could produce higher amounts of other antiviral proteins in response to virus such as those observed in this study: MX2, TRIM22, APOBEC3G, and of immunoregulators such as ERAP2, further preventing productive infection." (PMID 28243241, 2017). "Furthermore, increased levels of TAP-transporters (TAP1, TAP2), MHC I components B2M and HLAs, together with the ER chaperons calreticulin (CALR) and calnexin (CALN), and aminopeptidases ERAP1 and ERAP2 indicated upregulation of MHC I dependent antigen presentation with progressing infection." (PMID 37112941, 2023). "Indeed, as ERAP1 and ERAP2 expression has been demonstrated to be prompted by IFNγ stimulation, ERAPs production could be secondary to the innate immune response of the cells to infections, rather than to an immune response or an immune evasion mechanism." (PMID 32847031, 2020). "Despite still speculative the fact that ERAP2/Iso3 may exert such an effect cannot be ruled out: this, in turn, could lead to an altered peptide processing, which could confer an advantage/disadvantage against infections by presenting a more/less immunogenic antigen repertoire." (PMID 32847031, 2020).
infectious disease (5 papers, 2020 to 2023). A disorder directly resulting from the presence and activity of a microbial, viral, or parasitic agent in humans. "Polymorphisms in ERAP2 have been associated with predisposition to a number of autoimmune and infectious diseases, including chronic hepatitis C infection." (PMID 36071064, 2022). "The investigation of epistasis interaction between ERAPs and HLA variants is also essential in order to properly disclose the mechanism through which ERAP1 and ERAP2 influences infectious diseases and the process of antigen presentation." (PMID 32183384, 2020). "In this review, we have summarized the recent knowledge on the biology of ERAP1 and ERAP2 enzymes and their possible links to several infectious diseases." (PMID 32183384, 2020).
bacterial infection (2 papers, 2021 to 2024). "In addition, viral and also perhaps bacterial infections induce, in rs2248374G individuals, the expression of a third truncated transcript giving a shortened protein devoid of enzymatic activity but nevertheless possibly capable of interfering with ERAP1 and ERAP2 function." (PMID 39906739, 2024).
ERAP2 also shares sentences with these, for which no sentence is quoted: juvenile idiopathic arthritis (3 papers); rheumatoid arthritis (3); cervical intraepithelial neoplasia (2); immune diseases (2); lymphoma (2); ovarian carcinoma (2); systemic lupus erythematosus (2); uveitis (2); acute myeloid leukemia (1); adenoma (1); AIDS (1); asthma (1); atherosclerosis (1); celiac disease (1); cerebrovascular disease (1); cholera (1); colon adenocarcinoma (1); dystocia (1); gastric adenocarcinoma (1); glioblastoma (1); HELLP syndrome (1); hepatitis B infection (1); Hepatitis C (1); kidney cancer (1); neutropenia (1); Obesity (1); pneumonia (1); pregnancy disorder (1); primary sclerosing cholangitis (1); renal clear cell carcinoma (1).
A further 9 diseases each share a sentence with ERAP2 in 1 paper.